ZEB1 (zinc finger E-box binding homeobox 1)
Diseases named in the same sentence as ZEB1 in open-access papers (continued):
Sharing a sentence is not in itself a finding about the gene and the disease.
bladder cancer (continued). "Zeb1 has been reported to be an important molecule that drives bladder cancer cell motility." (PMID 23844063, 2013). "In addition, we examined the functional significance of miR-23b and identified Zeb1 as a direct target of miR-23b in bladder cancer." (PMID 23844063, 2013). "In human bladder cancer cell lines, we observed a direct correlation between E-cadherin and p63 expression, and an inverse correlation between these markers and Zeb-1, Zeb-2, and vimentin, indicating they cluster into unique “epithelial” and “mesenchymal” subsets." (PMID 22253920, 2012). "Of note, ZEB1/2, the miR205 targets in bladder cancer, were not affected by LEADR loss." (PMID 40461454, 2025). "Similarly, NEAT1 targeted miR‐448 to enhance ZEB1 expression in bladder cancer." (PMID 32596993, 2020). "Additionally, miR-200 regulates EMT in bladder cancer cells through decreasing ZEB1 expression." (PMID 28978061, 2017). "In addition, stromal cells in colorectal, breast, lung, and bladder carcinomas have been found to be ZEB1-positive, suggesting that paracrine ZEB1 signaling could be responsible for E-cadherin down-regulation in parts of the tumor." (PMID 27023622, 2016). "By acting as a ceRNA for miR-655, VIM-AS1 competed with ZEB1 for miR-655 binding, therefore eliminating the miR-655-mediated suppression of ZEB1, finally promoting EMT in both high- and low-metastatic bladder cancer cells and enhancing cancer cell metastasis." (PMID 33902589, 2021). "Via serving as a ceRNA for miR-655, VIM-AS1 competed with ZEB1 for miR-655 binding, therefore eliminating miR-655-mediated suppression of ZEB1, finally affecting EMT in both high- and low-metastatic bladder cancer cells and cancer cell metastasis." (PMID 33902589, 2021). "To further explore the combined effects of VIM-AS1 and ZEB1 on bladder cancer metastasis, we cotransfected T24 cells with si-VIM-AS1 and ZEB1, and cotransfected RT24 cells with VIM-AS1 and si-ZEB1." (PMID 33902589, 2021). "It (5–20 μM) can block the EMT of human bladder cancer cells via COX-2/MMP2,9/SNAIL, ZEB1, and miR200c/ZEB1 pathways." (PMID 31766574, 2019). "Besides, previous studies found that the down-regulation of miR-200c and miR-141 is associated with elevated ZEB1, and the down-regulation of miR-200c is also coupled with the down-regulation of BMI-1 and E2F3, which play an important role in the invasion, migration, and EMT of bladder cancer." (PMID 30323832, 2018). "The experiments in vitro suggested that knockdown of ZFAS1 repressed bladder cancer cell proliferation via up-regulating KLF2 and NKD2 expression, and inhibited cell migration and invasion via down-regulating ZEB1 and ZEB2 expression." (PMID 29678899, 2018). "Down-regulation of N-cadherin, vimentin, fibronectin, Zeb1, Twist, and Snail and up-regulation of E-cadherin were observed in CLCA4 overexpressed bladder cancer cells." (PMID 29190973, 2017). "In bladder cancer cells LY294002, a PI3K inhibitor, inhibits phosphorylation of AKT and GSK3β, and ZEB1 expression due to inhibition of β-catenin/transcription factor 4 (TCF4) complex binding and transcriptional activity on ZEB1 promoter." (PMID 26098771, 2015). "Luciferase reporter assays demonstrated that Zeb1, a crucial regulator of epithelial-to-mesenchymal transition (EMT), is a direct target of miR-23b in bladder cancer." (PMID 23844063, 2013). "lncRNA-UCA1 induces EMT in bladder cancer cells by up-regulating the expression levels of zinc-finger E-box-binding homology boxes 1 and 2 (ZEB1 and ZEB2), and it regulates bladder cancer cell EMT through the tumor suppressor hsa-miR-145 and its target gene FSCN1." (PMID 40689207, 2025). "More importantly, the effects of VIM-AS1 on both cell lines were significantly reversed by miR-655, indicating that VIM-AS1 acts as a ceRNA to competitively bind to miR-655, therefore rescuing ZEB1 expression and promoting EMT and metastasis in bladder cancer cells." (PMID 33902589, 2021).
bladder cancer (continued). "Coexpression analysis based on 405 bladder cancer samples of TCGA project revealed the apparently negative correlation between expressions of ZEB1 and miR-200b-3p or miR-200c-3p." (PMID 34811353, 2021). "Furthermore, ΔNp63α‐mediated expression of miR‐205 contributed to the regulation EMT in bladder cancer cells, and that miR‐205 prevented EMT through suppression of ZEB1 and ZEB2." (PMID 29150940, 2018). "Thus, knockdown of ZFAS1 repressed bladder cancer cell proliferation via up-regulating KLF2 and NKD2 expression, and inhibited cell migration and invasion via down-regulating ZEB1 and ZEB2 expression." (PMID 29678899, 2018). "Thus, we included TGFBR, which is connected to SMADs, and the chemokine (C-X-C motif) receptor 1 (CXCR1) connected to ZEB1 and SNAI1 in the bladder cancer model." (PMID 28775339, 2017). "In clinicopathological interpretation, increased ZEB1 and ZEB2 expression have been reported in human bladder carcinoma tissue, and ZEB2 represented as an independent factor of poor prognosis in the radiotherapy treated bladder cancer patients." (PMID 27058893, 2016). "In this study, we found that miR-429 can mediate suppression of EMT by reducing ZEB1 and β-catenin, but it is still not clear how miR-429 targeting network coordinated during bladder cancer progression." (PMID 27058893, 2016). "Additionally, in bladder cancer, HIF-1α promotes ZEB1 expression and EMT." (PMID 30541610, 2018).
osteosarcoma (59 papers, 2012 to 2025). A usually aggressive malignant bone-forming mesenchymal neoplasm, predominantly affecting adolescents and young adults. "For instance, the gene encoding Zeb1 (Tcf8) is induced by estrogen and/or progesterone in chick oviduct, mouse uterus, human smooth muscle cells, and an osteosarcoma cell line, although these effects vary among estrogen-sensitive cell lines." (PMID 22413003, 2012). "EMT can be activated by the overexpression of EMT activating factors and pathways, and in osteosarcoma, this mechanism could be mediated by high levels of the Zinc finger E-box-binding homeobox 1 (ZEB1), associated with increased proliferation and invasion and with poor prognosis in patients." (PMID 38534381, 2024). "Elevated levels of Zeb1 have been correlated with metastasis and poor prognosis in various cancers, including osteosarcoma." (PMID 40075892, 2025). "ZEB1 is overexpressed in osteosarcoma correlating with greater cancer cell migratory and invasive capacity." (PMID 40442778, 2025). "For example, it has been shown to cooperate with Twist and ZEB1 to reinforce the mesenchymal phenotype in osteosarcoma cells." (PMID 40075892, 2025). "On the contrary, however, exosome‐mediated miR‐144‐3p has been verified to promote ferroptosis in osteosarcoma via regulating zinc-finger E-box-binding homeobox 1 (ZEB1)." (PMID 38802766, 2024). "In individuals with osteosarcomas, such raised levels lead to greater ZEB1 and SEB2 expression through the suppression of miRNA-200." (PMID 39015175, 2024). "As an additional resistance model, we used the human osteosarcoma cell line U2OS with constitutive Zeb1 expression." (PMID 39009641, 2024). "Osteosarcoma tissue-derived exosomes promote ferroptosis to inhibit osteosarcoma progression via the miR-144-3p/ZEB1 axis." (PMID 38216595, 2024). "Decitabine exposure in osteosarcoma reduces the protein expression of the metastasis-associated markers VIMENTIN, SLUG, ZEB1, and MMP9, with a concurrent decrease in mRNA expression of the known stem cell markers SOX2, OCT4, and NANOG." (PMID 37197432, 2023). "Another direct target for miR-429 is ZEB1 which inhibition results in the induction of apoptosis in osteosarcoma and thyroid cancer cells." (PMID 36158660, 2022). "Previous studies have found that miR-126 can affect the biological function changes of osteosarcoma cells by regulating ZEB1." (PMID 35582235, 2022). "High expression of either SIAH 1 or 2 is correlated with a shortened ZEB1 half-life in human osteosarcoma." (PMID 35454770, 2022). "ZEB1 was identified as a downstream gene of miR-217, suggesting that HOTAIR can mediate osteosarcoma progression by upregulating ZEB1 expression via acting as a competitive endogenous RNA (ceRNA) via miR-217." (PMID 34576322, 2021). "ZEB1 was shown to be closely related to the EMT in osteosarcoma, and miR-126 and miR-708-5p played an inhibitory role in the proliferation and invasion of osteosarcoma cells by directly targeting ZEB1 and subsequently suppressed the EMT." (PMID 34109218, 2021). "PCAT6 increases ZEB1 levels by sponging endogenous miR-143-3p, which supports the malignant phenotype of osteosarcoma cells." (PMID 34327141, 2021). "Mechanistic studies revealed that PCAT6 can increase ZEB1 levels by sponging endogenous miR-143-3p, and the upregulation of ZEB1 can aggravate the malignant phenotype of osteosarcoma cells." (PMID 34327141, 2021). "ZEB1 promotes tumor invasion and metastasis by inducing the EMT in osteosarcoma, causing carcinoma cells to acquire cancer stem cell properties such as self-renewal." (PMID 34109218, 2021). "It has been previously shown that AUF1 stabilizes the EMT inducer ZEB1 in osteosarcoma and thyroid cancer cells." (PMID 32759946, 2020). "Reversely, after knockdown of lncRNA NR_027471, the expression of E-cadherin was downregulated, whereas that of ZEB1, Snail, and fibronectin was upregulated in osteosarcoma cells compared to pLKO.1-Vector group." (PMID 33117693, 2020).
osteosarcoma (continued). "In cultured cells, both Western blot and real-time PCR showed much stronger Zeb1 expression in osteosarcoma MG63 and U2OS cells than in control hFOB1.19 osteoblasts." (PMID 30580326, 2018). "The expression of Zeb1 in human osteosarcoma samples was assessed by Western blot and real-time PCR." (PMID 30580326, 2018). "Our results also showed that both naringin exposure and Zeb1 silencing significantly suppressed osteosarcoma cell migration in Transwell assays." (PMID 30580326, 2018). "Using human osteosarcoma cell lines as experimental model, in the present study we provide in vitro and in vivo evidence that naringin suppresses proliferation and metastasis of osteosarcoma cells by inhibiting the expression of Zeb1." (PMID 30580326, 2018). "Upon exposure to naringin (10 or 20 μmol/L) for 24 h, Zeb1 protein and mRNA levels were dramatically decreased, in dose-dependent manner, in both osteosarcoma cell lines." (PMID 30580326, 2018). "Our expression analyses confirm that Zeb1 is highly expressed in osteosarcoma specimens and cell lines." (PMID 30580326, 2018). "Here, we show that naringin inhibits proliferation and invasion and induces apoptosis in human osteosarcoma cells by inhibiting zinc finger E-box binding homeobox 1 (Zeb1), a transcriptional repressor of epithelial differentiation involved in tumor metastasis." (PMID 30580326, 2018). "EMT inducer ZEB1 was the target gene of miR-429 and the expression of ZEB1 was negatively related to the miR-429 expression in osteosarcoma." (PMID 28694763, 2017). "Rescued miR-144-3p subsequently downregulates ZEB1 reducing osteosarcoma metastatic capacity." (PMID 40442778, 2025). "Notably, elevated expression levels of ZEB1 were observed in osteosarcoma tissue compared to healthy bone tissue." (PMID 38613804, 2024). "Furthermore, A high expression of ZEB1 is highly correlated with invasion and metastasis of osteosarcoma." (PMID 38652223, 2024). "Despite that direct evidence of ZEB1 SUMOylation in osteosarcoma is still missing, these data suggest that targeting ZEB1 by reducing its SUMOylation could possibly reduce EMT and invasiveness." (PMID 38534381, 2024). "Interestingly, the inhibition of ZEB1 transcription facilitates caspase 3−mediated apoptosis by downregulating the NFκB/iNOS pathway, thus inhibiting the proliferation of MG-63 osteosarcoma cells." (PMID 35454770, 2022). "One study showed that naringin treatment suppressed cell migration, invasion, and proliferation, and promoted apoptosis and cell cycle arrest in MG63 and U2OS human osteosarcoma cells through blockage of zinc finger E-box binding homeobox 1 (Zeb1), which plays a role in tumor metastasis." (PMID 33854437, 2021). "Furthermore, CAT104 was found to regulate miR-381 to target zinc finger E-box-binding homeobox 1 (ZEB1) as well as Wnt/β-catenin pathways to exert its oncogenic effects on osteosarcoma cells." (PMID 34130697, 2021). "In osteosarcoma, miR-643 was revealed to suppress tumorigenesis by ZEB1." (PMID 33221765, 2020). "Furthermore, AUF1 stabilized the mRNA of the pro-EMT transcription factor ZEB1 in osteosarcoma and thyroid cancer cells." (PMID 32759946, 2020). "A previous study demonstrated a close relationship between miR-126 and ZEB1 in osteosarcoma." (PMID 31007650, 2019). "Finally, the transcript and protein levels of ZEB-1 are significantly higher in osteosarcoma tissues when compared with normal bone tissues, ZEB-1 levels being increased in patients with lung metastasis." (PMID 29761075, 2018). "Zeb1 has also been shown to be upregulated in osteosarcoma, and to contribute to its development." (PMID 30580326, 2018). "MiR-429 may suppress the progression and metastasis of osteosarcoma by down-regulating the ZEB1 expression." (PMID 28694763, 2017).
osteosarcoma (continued). "Similarly, in malignant bone tumors, osteosarcomas, elevated levels of ZEB1 are detected compared to normal bone and ZEB1 expression is higher in metastatic osteosarcoma in comparison with the group without metastases." (PMID 28556516, 2017). "It is required to investigate whether lncRNA SCAMP1 targets ZEB1 in osteosarcoma cells." (PMID 35992869, 2022). "Furthermore, EMT inactivation inhibited proliferation, migration, invasion, and in osteosarcoma by targeting zinc finger E-box-binding protein 1 (ZEB1) through inactivation of c-Jun N-terminal kinase (JNK) and JAK1/signal transducer and activator of transcription 3 (STAT3) pathways." (PMID 33472642, 2021). "In patients with osteosarcoma and lung metastasis, USP43 deubiquitinates ZEB1 and maintains its transcription, resulting in increased invasion of osteosarcoma cells via inducing EMT." (PMID 38613804, 2024). "SPRY4-IT1 can also regulate the expression of ZEB1 and ZEB2 by sponge miR-101 activity, thereby promoting the progression of osteosarcoma." (PMID 39015175, 2024). "Theabrownin inhibited NF‐κB signaling to reduce the expression levels of ZEB1, Slug, and Snail1 expression levels, increase E‐cadherin levels, and inhibit EMT, facilitating inhibition of osteosarcoma migration." (PMID 37688511, 2023). "JNK and P13/AKT signaling pathways are induced in osteosarcoma cells via axes lncRNA CAT104—miR-381—mRNA ZEB1, lncRNA MEG3—miR 127—mRNA ZEB1, and lncRNA ATB—miR-200—mRNA ZEB1 and ZEB2." (PMID 37232745, 2023). "The expression of E-cadherin was upregulated, while that of zinc finger E-box-binding homeobox 1 (ZEB1), Snail, and Fibronectin was downregulated in lncRNA NR_027471-overexpressing osteosarcoma cells compared to pLVX-Vector group." (PMID 33117693, 2020). "We first confirmed high Zeb1 expression in human specimens and in human MG63 and U2OS osteosarcoma cell lines." (PMID 30580326, 2018). "Remarkably, the osteosarcoma U2OS cells internalized significant amount of EVs and the incubation with EVs led to an increase in the expression of EMT genes Zeb1 and Snail and of the stem cell markers Nanog, Oct4 and Sox2." (PMID 24404144, 2014). "Silencing of TTYH1 inhibited the migration and invasion of the U2OS osteosarcoma cells and reduced the expression of epithelial-mesenchymal transition (EMT)-related factors such as SNAIL, Zinc E-Box Binding Homeobox 1 (ZEB1), matrix metalloproteinase 2 (MMP2), MMP9, and N-cadherin." (PMID 35455021, 2022). "Downregulation of GAS5 in hFOB 1.19 and U2OS osteosarcoma cells enhanced their migration and invasion, along with an upregulated epithelial–mesenchymal transition (EMT), as evidenced by downregulated E-cadherin and upregulated vimentin, ZEB1, and ZEB2." (PMID 34386496, 2021). "Consequently, induced ZEB1 and Snail can mediate EMT activation, leading to the repression of osteosarcoma cells to CP chemotherapy." (PMID 32503307, 2020). "The limitations of this study include that we did not investigate the effects of ectopic ZEB1 over-expression on cell proliferation and invasion activity of miR-409-3p-expressing osteosarcoma cells and that the number of samples in this study is small thus multi-center trial is still needed." (PMID 30846940, 2019).